METTL16 (methyltransferase 16, RNA N6-adenosine)
Diseases named in the same sentence as METTL16 in open-access papers (continued):
Sharing a sentence is not in itself a finding about the gene and the disease.
cancer (continued). "METTL16 has been investigated for its role in regulating cancer progression by modulating target genes through m6A modification." (PMID 40095756, 2025). "Collectively, these efforts are expected to further uncover the central role of METTL16 in cancer biology and provide novel strategies for precision oncology and immunotherapy." (PMID 41322419, 2025). "Studies have shown that copper levels are significantly elevated in GC tissues, especially in malignant tumors, and METTL16 mediates cuproptosis by m6A modification of FDX1 mRNA." (PMID 41322419, 2025). "Extensive research has been conducted on the role of METTL16 in regulating cancer progression through m6A modification of target genes, including U6 snRNA, MALAT1, XIST, and RAB11B‐AS1, and mRNA (MAT2A, VPS33B, FGFR4, and GPX4)." (PMID 40095756, 2025). "METTL16, one of the m6A methyltransferases, is recognized as the second m6A methyltransferase discovered and extensively studied in human cancers." (PMID 39248438, 2024). "Meanwhile, METTL16 deficiency directly impeded the synthesis of FADD and DR5 proteins, thereby impairing apoptosis and promoting cancer cell survival." (PMID 39289775, 2024). "Treatment with Notch activators augmented METTL16 knockdown–mediated cancer cell invasion and migration." (PMID 39101773, 2024). "In this context, our study focused on METTL16, an m6A writer, which has been shown to play a dual role in cancers." (PMID 39434688, 2024). "Mechanistically, we have characterized that a set of genes related to mRNA translation and cancer metabolism are directly regulated by the METTL16 in HCC." (PMID 38302992, 2024). "Conversely, treatment with Notch inhibitors invalidated METTL16 overexpression–mediated suppression of cancer cell invasion and migration." (PMID 39101773, 2024). "It was likely to due to the METTL5 and METTL16 genetic variations function diversely on multiple cancers, and influence the progression of EOC through transcription modification." (PMID 38370381, 2024). "Of note, the mechanisms for METTL16-regulated CCA cell growth appears to be different from those reported for some other cancer types." (PMID 37817227, 2023). "In the respiratory system, research has shown that exposure to PM2.5 induces pulmonary vessel damage in an m6A-dependent manner through METTL16, providing new insights into the mechanisms of chronic obstructive pulmonary disease and cancer." (PMID 38045858, 2023). "We found that among the METTL family members, METTL16 is a vital gene for the survival of the vast majority of cancer cells, implying its functional importance in cancer." (PMID 37182151, 2023). "METTL16 showed divergent expression in cancers, even in the same cancer, it has been found in different expressions in different studies, the underlying reasons should be further studied." (PMID 38045858, 2023). "Usually, METTL16 leads to bad prognosis; however, the effects on cancer prognosis can be modulated by other genes." (PMID 38045858, 2023). "Surprisingly, two large-scale CRISPR-Cas9 screening datasets suggest that METTL16 is a more important gene for the survival of various types of human cancer cells than any other METTL gene." (PMID 39872957, 2023). "It still requires more strongly evidences to prove that METTL16 participates in the regulation of cancer progression through inducing m6A modification of mRNAs or ncRNAs." (PMID 37773181, 2023). "METTL16 has been identified as a potential gene involved in the initiation and progression of cancer." (PMID 38045858, 2023). "Meanwhile, analyses suggested that METTL16 is the most essential gene for the survival of the vast majority of cancer cells among all the METTL family members, which indicates a potential role in cancer treatment." (PMID 37069649, 2023). "Downregulation of METTL16 has recently been related to cancer progression and poor overall survival in patients with hepatocellular carcinoma and tumors of the endocrine system." (PMID 37927399, 2023).
cancer (continued). "Another lncRNA, named lncRNA RAB11B-AS1, has recently been found to directly bind to METTL16, promoting cancer development in an m6A-dependent manner by decreasing lncRNA stability." (PMID 38045858, 2023). "METTL16 can regulate protein translation and aggravate cancer development by directly binding to TIC." (PMID 38045858, 2023). "Accordingly, it was reported that the Mettl16 gene is essential for the survival of the vast majority of human cancer cells, for mouse development and in adult mice." (PMID 36553579, 2022). "In summary, loss-of-function screens of cancer cell lines support the biological importance of several METTLs, notably METTL1, METTL3, METTL14, METTL16 and METTL17, in promoting cancer cell growth and survival." (PMID 34285249, 2021). "M6A methyltransferase [such as METTL3, METTL14, and METTL16] participates in the progression of malignant tumors by read, write, or erase m6A on bound RNA24." (PMID 33741902, 2021). "In summary, the present study reveals that METTL16 has a cancer‐promoting effect in GC and high expression of METTL16 indicates poor prognosis of GC." (PMID 34075693, 2021). "Decreased expression of METTL16 is linked with activation of numerous metabolic pathways in HCC, suggesting a possible role of METTL16 in metabolic reprogramming–a hallmark of cancer." (PMID 33671635, 2021). "METTL16 does appear to be vital for the proliferation/survival of a number of cancer cells and has been identified in a number of screens for essential genes." (PMID 31940410, 2020). "Among these cancer relapse-relevant genes, METTL16, FTO, EIF3D, and EIF3I were good prognostic factors, while TRA2A, HNRNPA2B1, and YTHDC2 were bad ones." (PMID 33273988, 2020). "It suggests that targeting METTL16 could be a promising strategy for cancer prevention and treatment." (PMID 41459114, 2026). "Inducing ferroptosis by inhibiting METTL16 could therefore address treatment resistance in cancer patients." (PMID 41459114, 2026). "METTL16-targeted therapy may complement immunotherapy for cancers characterized by METTL16-driven immunosuppressive microenvironments, but this hypothesis requires further validation." (PMID 41459114, 2026). "However, in certain cancer subtypes, elevated METTL16 expression correlates with more favorable clinical outcomes, highlighting its context-dependent role." (PMID 41459114, 2026). "In addition to its role in modulating U6 snRNA, METTL16 regulates the expression and function of non-coding RNAs (ncRNAs), long non-coding RNAs (lncRNAs), and ribosomal RNA (rRNA) in cancer." (PMID 41459114, 2026). "In addition to acting as a methyltransferase, METTL16 can also facilitate mRNA translation in an m6A-independent manner, thus regulating cancer development and progression." (PMID 41695366, 2026). "Ongoing research into the molecular mechanisms of METTL16 may enable targeted interventions in its regulatory pathways, opening new possibilities for precision cancer therapy and prognostic evaluation." (PMID 41459114, 2026). "Furthermore, some genes (e.g., FXR2, METTL16) generally show copy number losses in pan-cancer, while some (e.g., IGF2BP3, YTHDF1) primarily exhibit copy number amplifications." (PMID 40867324, 2025). "Human Methyltransferase-like 16(METTL16) is an independent N6-methyladenosine (m6A) methyltransferase and it plays an important role in the process of cancers by forming m6A marks on S-adenosylmethionine (SAM) synthetase pre-mRNA and U6 small nuclear RNA (U6 snRNA)." (PMID 40015977, 2025). "Additionally, while m6A methyltransferases like METTL16 have received limited attention, they are emerging as critical regulators of ferroptosis in cancer." (PMID 40271153, 2025). "We found that METTL16 expression was significantly higher in the cancer tissues." (PMID 39744432, 2025). "High METTL16 expression has also been observed in various human cancer tissues." (PMID 41322419, 2025). "It was also observed that overexpression of METTL16 inhibited cancer growth." (PMID 40448344, 2025).
cancer (continued). "The METTL16 regulators have been connected with various types of cancers." (PMID 40015977, 2025). "Currently, small-molecule inhibitors and RNA interference strategies targeting METTL16 are showing promising results in preclinical studies, and may eventually serve as novel cancer treatment approaches." (PMID 41322419, 2025). "Given that METTL16 is highly expressed in CC, we speculated that METTL16 may have pro-cancer effects in CC." (PMID 39744432, 2025). "In conclusion, the KDM3A/METTL16/PDK1 axis plays an important role in cancer development and TKI resistance, which may offer new prognostic biomarkers and therapeutic targets for TKI resistance in the future." (PMID 42004224, 2025). "Our studies also proved that METTL16 closely related with the immune infiltration in human cancers." (PMID 40015977, 2025). "These functions of METTL16 underscore its critical roles in cell proliferation, stress responses, and metabolic homeostasis, suggesting a unique contribution to tumorigenesis and cancer progression." (PMID 41322419, 2025). "Our previous study showed that, amongst the human METTL family with over 30 members, METTL16 is the most essential one for the survival of cancer cells; in addition, METTL16 directly interacts with rRNAs and translation machinery to enhance translation efficiency." (PMID 38302992, 2024). "It is also necessary to dissect its function in normal bioprocess and development to comprehensively evaluate whether METTL16 can serve as a good target for cancer therapy." (PMID 38302992, 2024). "One such RNA-bindingprotein that regulates the most prevalent eukaryotic RNA modification, N6-methyladenosine (m6A), is the methyltransferase-likeprotein 16 (METTL16), which plays an oncogenic role in cancers bycofunctioning with other nucleic acid-binding proteins." (PMID 38665670, 2024). "METTL16 has been extensively investigated, with numerous studies documenting its involvement in cell proliferation, metastasis, and chemotherapy in various cancer types." (PMID 38334797, 2024). "Overall, our studies indicate that the oncogenic function of METTL16 relies on its role in reprogramming mRNA translation in cancer (e.g., HCC) cells, and highlight the therapeutic potential of targeting the METTL16/eIF3a axis and mRNA translation program for cancer treatment." (PMID 38302992, 2024). "A recent study showed that METTL16 is one of themost importantgenes for various cancer cell survivability, especially among thehuman methyltransferase family, suggestingthe promising potential of METTL16 inhibition via small moleculesas a new anticancer strategy." (PMID 38665670, 2024). "We observed multiple METTL16-dependent sites in the cancer-associated MALAT1 lncRNA, however, A8290 was not methylated in vitro." (PMID 37935679, 2023). "Therefore, the mechanisms mediating METTL16 actions in different cancer types are likely to be context dependent." (PMID 37817227, 2023). "Nevertheless, it remains unclear whether METTL16 mediated m6A modification of lncRNAs can regulate AURKA activation in cancer progression." (PMID 37773181, 2023). "However, the investigation of METTL16 in cancer is limited and there are only a few reports available to date." (PMID 38045858, 2023). "METTL16 is an m6A methyltransferase that modifies several pre- and non-coding RNAs, promotes translation and carcinogenesis, and is an important potential target for cancer treatment." (PMID 37863889, 2023). "In addition, the results of immunohistochemistry (IHC) staining of CRC samples and adjacent para-cancer tissue further verified that METTL16 expression was enhanced in CRC tissues." (PMID 37340443, 2023). "Further studies are still necessary to unravel the specific roles of METTL16 in cancer." (PMID 37612540, 2023). "However, further experiments are necessary to fully understand the role of METTL16 and RNAs in cancer." (PMID 38045858, 2023).
cancer (continued). "Future studies into the role of METTL16 in cancer may provide insight into this mechanism, and better understanding of the role of the VCR linker region may provide direction toward therapeutics for METTL16-driven tumors." (PMID 37504262, 2023). "Collectively, these results suggest an important role of METTL16 in cancer immune response." (PMID 36158188, 2022). "In addition to the METTL14–METTL3 complex, METTL16 has been discovered more recently, and its regulatory role in cancer has attracted some discussion." (PMID 36226062, 2022). "It will now be important to investigate METTL16 function in MAT2A regulation in pluripotent stem cells and cancer models, as these cell types have an unusually high dependence on methionine, and altered metabolism is a hallmark of cancer." (PMID 36553579, 2022). "However, CBLL1 and METTL16 have mainly been studied in cancers and act as oncogenic markers to promote the development and progression of tumors." (PMID 36685841, 2022). "However, the specific role of METTL16 in the development of cancer, especially GC, and related regulatory mechanism are still unclear." (PMID 34075693, 2021). "METTL16 recognizes the RNA triple helix located at the 3′ end of cancer-promoting MALAT1." (PMID 33671635, 2021). "However, a proper biological function of both METTL16 as a “writer” and m6A RNA as epitranscriptomic features must be specified, especially in cancer cells and during DNA repair processes." (PMID 34357041, 2021). "We also observed cytoplasmic METTL16 localization in a number of other cell types representing normal cells as well as different stages of cancer suggesting that this may be a more general finding relevant to all cell types." (PMID 31940410, 2020). "Furthermore, it proposes that targeting METTL16 represents a promising avenue for cancer therapy." (PMID 41459114, 2026). "Furthermore, lncRNAs such as X inactive specific transcript (XIST) and lnc-CSMD1-7 have been shown to interact with METTL16, and these interactions may influence cancer metastasis and poor prognosis." (PMID 41459114, 2026). "These interactions enable METTL16 to engage with proteins involved in RNA metabolism, cellular signaling, and DNA repair, thereby modulating its methyltransferase activity and localization in response to cellular stresses, which is critical for cancer cell adaptation." (PMID 41459114, 2026). "METTL16 may promote or prevent cancer depending on cancer type (see recent review)." (PMID 41007290, 2025). "Besides the nucleolar localization, METTL16 also directly associates with eIF3a/b, but not other eIFs, in the cytosol to enhance mRNA translation in cancer cells." (PMID 38302992, 2024). "METTL16 is also important for the maturation of the metastasis-associated lung adenocarcinoma transcript 1 (MALAT1) lncRNA, which may act as either an oncogene or a tumor suppressor depending on the cancer type." (PMID 37612540, 2023). "We believe METTL16 could be a new target for cancer treatment." (PMID 39872957, 2023). "In summary, METTL16 plays a multifaceted role in regulating immune cell function, antitumor immunity, and the TME across multiple cancer types." (PMID 41322419, 2025). "In breast cancer, METTL16 regulates GPX4 expression, inhibiting ferroptosis and promoting cancer cell proliferation." (PMID 41256854, 2025). "Our findings unveil a novel METTL16-MXD4 oncogenic axis crucial for AML progression, establishing small-molecule inhibition of METTL16 as a potential therapeutic approach in leukemia and providing a new strategy to target MYC activity in cancer." (PMID 40946103, 2025). "Mechanistically, METTL16 enhances FBXO5 mRNA stability via m6A modification, leading to elevated FBXO5 expression, which promotes cancer cell proliferation, migration, invasion, and EMT." (PMID 41322419, 2025).
cancer (continued). "While the potential for cancer treatment through targeting METTL3 and METTL16 has been extensively demonstrated, it is important to note that these genes are essential for cell survival." (PMID 39333489, 2024). "Specifically, we aim to investigate how METTL16, an m6A writer gene, interacts with key downstream targets, such as CAPN2 and MROH8, to influence cancer metastasis." (PMID 39434688, 2024). "According to high throughput cancer cell line CRISPR screenings, METTL16 appears to play a more important role in cancer cell survival and proliferation than METTL3." (PMID 37817227, 2023). "Analysis of the genetic expression data from CCLE indicated that METTL16 and ALKBH5 expression levels were lower in PDA cell lines than in most other cancer cell lines." (PMID 36158188, 2022). "However, METTL16 mutants that have no methylation activity or even improved activity, such as the cancer-associated mutant R200Q, maintained their interactions with eukaryotic initiation factors 3a and 3b, an interaction that promotes cancer via translation of certain mRNAs." (PMID 41007290, 2025). "A large number of studies of m6A regulatory mechanisms have investigated classical m6A regulators, such as METTL3, METTL14, WTAP, METTL16, FTO, ALKBH5, YTH family proteins, and IGF2BPs; anti-cancer target drugs targeting METTL3 and FTO have been proven to be effective against cancer." (PMID 38970366, 2024). "The role of the U6 spliceosomal snRNA methyltransferase METTL16 in cancer has not yet been well studied." (PMID 37612540, 2023). "Although METTL16 destabilizes disheveled segment polarity protein 2 (DVL2) mRNA by m6A modification and suppresses its expression, when the expression of DVL2 increases due to decreased METTL16 expression, Wnt/β‐catenin signaling is activated and cancer progression occurs." (PMID 40448344, 2025). "Additionally, most current studies on METTL16 have focused on its roles in RNA splicing, SAM homeostasis, and cancer cell–intrinsic signaling, rather than the TME." (PMID 41322419, 2025).
endocrine system tumors (5 papers, 2020 to 2023). "It was observed that METTL16 plays an important role in the development of endocrine system tumors, and METTL16 is a protective gene." (PMID 35047058, 2022). "In endocrine system tumors, the reduced expression of METTL16 leads to worse survival." (PMID 37859814, 2023). "We observed that WTAP, METTL16 and IGF2BP3 play important roles in the development of endocrine system tumors, WTAP, METTL16 are protective genes, IGF2BP3 is danger genes." (PMID 33237039, 2020). "In general, it can be considered that WTAP, METTL16 and IGF2BP3 play important roles in the development of endocrine system tumors, WTAP, METTL16 are protective genes, IGF2BP3 is danger genes." (PMID 33237039, 2020). "Thus, METTL16 is considered a protective gene, suppressing the development of OC, HCC, and endocrine system tumors." (PMID 33671635, 2021).
adenocarcinoma (1 paper, 2021). A common cancer characterized by the presence of malignant glandular cells.
digestive system cancer (1 paper, 2026). A primary or metastatic malignant neoplasm involving any part of the digestive system. "By comprehensively summarizing the current literature on METTL16, we provide a theoretical basis for its application as a diagnostic and prognostic marker as well as a potential therapeutic target for digestive system cancers." (PMID 41695366, 2026).
hematological malignancies (1 paper, 2022). "Given that METTL16 is pivotal for the regulation of DNA-damage response and erythropoiesis, the altered METTL16 expression and/or activity may also be associated with diseases such as hematological malignancies." (PMID 36307435, 2022).